OAS1 (2'-5'-oligoadenylate synthetase 1)
Diseases named in the same sentence as OAS1 in open-access papers (continued):
Sharing a sentence is not in itself a finding about the gene and the disease.
viral infection (continued). "Specifically, we analyzed the effect of AdNrf2 alone or Nrf2 overexpression followed by infection with PR8 virus on the interferon-induced Mx1 and the OAS1 genes, which are involved in the innate immune response to viral infection." (PMID 22672594, 2012). "We then evaluated the expression of four interferon-stimulated genes (ISGs) acting on different steps of viral infection (i.e., OAS1, IFITM3, ISG15, and MxA) in lysates of nasal HAEs infected with each single virus or coinfected with the two viruses simultaneously or sequentially 1 or 4 days apart." (PMID 40366152, 2025). "Ostriches are the only avian species to possess both OAS1 and OASL, and the enzymatic activity of OAS1 may play a complementary role in specific viral infections." (PMID 40920862, 2025). "Building upon these studies, OAS1's pathway in viral infection response can be delineated." (PMID 39282474, 2024). "Notably, OAS1 functions as a dsRNA-activated antiviral enzyme, playing a crucial role in the innate immune response against viral infection." (PMID 39296547, 2024). "This comprehensive involvement makes OAS1 a key player in the immune defense against Ebola, contributing to both the immediate antiviral response and the regulation of systemic immune reactions that are critical during severe viral infections." (PMID 39282474, 2024). "Also, a transcriptome study of neuron cultures after viral infection detected upregulation of Ccl4, Cxcl10, Oas1, Irf1, and Irf7, an important modulator of the type I interferon process." (PMID 38189117, 2024). "OAS1 is induced earlier than OAS2 and OAS3 during dengue virus infection, and mutations of the different OAS members had been correlated with several viral infections." (PMID 37209263, 2023). "Likewise, OAS1 has a strong antiviral impact both in vivo and in vitro and protects cells from viral infection." (PMID 35884586, 2022). "Classical ISGs responsible for inhibition of viral infection include OAS1, MX1, and ISG15." (PMID 32760370, 2020). "The potential role of OAS3 in the recognition of CpG- and UpA-high mutants is consistent with its demonstrated preferential role in mediating RNAseL responses to a wide range of virus infections, and the frequent inactivity of OAS1 (and OAS2) in antiviral defence." (PMID 31276592, 2019). "The P protein was shown to specifically target the interferon-beta (Ifn-β), myxovirus resistance protein 1 (Mx1) and 2′-5′-oligoadenylate synthetase 1 (Oas1) genes, resulting in the decreased expression of these genes that are important in innate responses against viral infections." (PMID 27548204, 2016). "The OAS1 to-3 proteins have a characteristic polymerase activity, the 2’-5’ oligoadenylate (2–5A) synthetase activity, that is activated by double-stranded (ds)RNA in the context of a viral infection." (PMID 25738304, 2015). "One of the major antiviral mechanisms of interferon is the activation of OAS1, which leads to the production of short oligonucleotides that in the presence of viral infections activate ribonucleases that destroy viral mRNA within infected cells inhibiting viral replication." (PMID 23593233, 2013). "Variations in the human OAS1 gene that may be relevant to the outcome of virus infections have been reported." (PMID 17822564, 2007). "Moreover, IFI6 (p=0.002) and OAS1 (p=0.044) were upregulated in cases with high viral loads, which could be related to protection against severe forms of this viral infection." (PMID 37389217, 2023). "Fully defining these dsRNA features and their optimal contexts for OAS1 activation by viral or cellular RNAs is important because differing levels of pathway activation likely underpin regulation of distinct cellular processes or cell fates (e.g. apoptosis in response to viral infection)." (PMID 32678884, 2020).
viral infection (continued). "Nevertheless, the slight differences in 2′-5′OAS1 gene expression between rTGEV-wt and rTGEV-Δ7 infections could not explain the enhanced nuclease activity observed during mutant virus infection, as 2′-5′OAS1 mRNA level was even lower for rTGEV-Δ7 than for rTGEV-wt virus." (PMID 21695242, 2011). "The highest ratio in this set was two-fold and out of the top 10 specificities, 7 were in the Type I interferon signature (IFITM3, MX1, IFI6, IFI44L, ISG15, OAS1, IFIT3) and one encodes a protein that is activated by dsRNA as might be present in a viral infection (EIF2AK2)." (PMID 21366908, 2011). "In the absence of viral infection, cells often produce dsRNA as a stress response, and the accumulation of Aβ may be considered a stressor, causing inflammation, which increases the expression of OAS1." (PMID 39859237, 2025). "Meanwhile, the transcriptional levels of interferon-stimulated genes (ISGs) such as ISG15, ISG20, OAS1, OAS2, MX1, and MX2 were significantly up-regulated, and these ISGs play a crucial role in resisting viral infection." (PMID 41153955, 2025). "OAS1 and MAVS are Interferon Stimulated Genes (ISGs) which are up-regulated during active viral infections." (PMID 41468475, 2025). "When bat IRF7 was overexpressed in bat TB 1 Lu cells, we observed significant increases in the expression of IFN-β and OAS1 both before and after VSV-GFP virus infection." (PMID 40108733, 2025). "The induction of OAS1, OAS2, and OASL, which, as main sensors for viral infections, explains the induction of numerous interferon-induced proteins (e.g., IFIT1, IFIT2, IFI44, MX1, MX2)." (PMID 39062793, 2024). "Previous studies have identified that following viral infection, type I IFN signaling induces the production of the OAS family consisting of OAS1, OAS2, OAS3, and OAS-like (OASL) protein." (PMID 38650851, 2024). "In conclusion, the relevance of OAS1, IRF9, and IFI6 in controlling the viral infection was confirmed." (PMID 38731851, 2024). "In particular, OASL binds to RIG-I and activates and enhances RIG-I signaling; OAS1 binds to viral dsRNA and, together with DDX60, helps RIG-I recognize viral RNA and amplify viral-induced RIG-I-mediated type I IFN expression after viral infection." (PMID 36655136, 2023). "For example, upregulated genes OASL, OAS1, OAS2, and OAS3 belong to the OAS family, a group of antiviral enzymes induced by type I IFNs, which can locate and bind viral dsRNA after viral infection." (PMID 36655136, 2023). "ISGs products, including OAS1, OAS2, MX1, ADAR, and EIF2AK2, are major players in innate immune defence against viral infection." (PMID 36016774, 2022). "In our data, the enriched pathways were related to viral infections such as influenza A (MX1, OAS1, OAS2, OAS3, RSAD2, STAT1) and measles (MX1, OAS1, OAS2, OAS3, STAT1)." (PMID 35464437, 2022). "The resulting secreted IFNs inhibit virus infection by inducing the expression of ISGs—including protein kinase R (PKR), 2′-5′-oligoadenylate synthetase 1-(OAS1), ADAR1 and ribonuclease (RNAse) L—in the original and in neighboring cells." (PMID 35453767, 2022). "The antibodies were incubated with cells 2 h before viral infection, and then endogenous IFN-α, IFN-β, and OAS1 mRNA expression was examined by qRT-PCR at 24 hpi." (PMID 35062253, 2021). "These inhibitors were incubated with the cells 2 h before viral infection, and then endogenous IFN-α, IFN-β, STAT1, IRF7, and OAS1 mRNA expression were examined by qRT-PCR analysis at 24 hpi." (PMID 35062253, 2021). "Knockdown of NLRX1 leads to enhanced transcription levels of IFNb1, STAT2, and the 2′-5′-oligoadenylate synthetase 1 gene (OAS1) after viral infection, suggesting a negative regulatory role of NLRX1 on the IFN-β/STAT2/OAS1 axis." (PMID 33525590, 2021). "ISGs are effector molecules that mediate cellular innate immune responses to viral infections, including PKR, OAS1, Mx1, and Mx2." (PMID 32133381, 2020).
viral infection (continued). "For instance, OAS1 and OAS2 are responsible for the activation of ribonuclease L, which is part of the innate immune defense, during viral infection." (PMID 32155831, 2020). "Bat and human Oas1 genes have one similar ISRE, and OAS1 mRNA expression is moderately inducible by IFN or virus infection (40- to 80-fold) in bats, similar to our findings in human cells." (PMID 31719180, 2019). "The initial defense and adaptive immune responses against viral infection are performed by type I IFNs (IFN-α/β) such as RTP4, GBP1, OAS1, IFI27, and IF44L." (PMID 31665046, 2019). "Previous work has identified that following viral infection, type I IFN signaling induces the production of the 2′-5′-oligoadenylate synthetase (OAS) family, which include OAS1, OAS2, OAS3, and OAS-like (OASL) protein." (PMID 28580319, 2017). "Interferon signalling is essential for the production of anti-viral mediators (such as OAS1, Mx1, SP100, and TRIM22) to defend against virus infection." (PMID 28273165, 2017). "Pre-treatment with IFN-α14 highly induced the expression of ISGs such as MX1, OAS1, and PKR and upon virus infection, it efficiently suppressed viral replication compared with the other subtypes of IFN-α." (PMID 26694447, 2015). "Our study demonstrates increased intracellular HRV RNA load in CF HBE cells, which occurs during the early hours of virus infection despite preserved IFN-β and OAS1 responses." (PMID 26599098, 2015). "The interferon (IFN) response is an essential host defense program that limits viral infection and was shown here with the upregulation of many interferon-inducible genes including MX1, OAS1." (PMID 23881275, 2013). "Interestingly, these genes were also identified in cluster 1 of our analysis, which also exhibited high expression of OAS1 and OAS2, members of the 2′-5′ oligoadenylate synthetase (OAS) family known to be rapidly induced in response to viral infections." (PMID 37409113, 2023). "Viral infections generated IFNs, which were accompanied by the transcription of OASL, and activated IFN responsive pathways after upregulating IFN regulated genes including OAS1 and STAT1." (PMID 36765396, 2023). "Mx1 (MxA in humans) is established as an ISG that only reacts to IFN, but not directly to infection, whereas OAS1 can be induced by both virus infection and IFN." (PMID 37728614, 2023). "The formation of super-enhancers governing CXCL9/10/11, CCL7/8/13, IFITM1/2/3, OAS1 genes, but not housekeeping genes, was robustly decreased in SAFA mutation cells after virus infection." (PMID 35658050, 2022). "In addition, SL1 in the 5′ leader of SARS‐CoV‐2 genomic RNA interacts with 2′‐5′‐Oligoadenylate synthetase 1 (OAS1), which is a key enzyme driving the innate immune response to viral infection." (PMID 35429230, 2022). "At the gene level, we found that NF could significantly induce a set of ISG expressions, such as MCL1, IFITM3, B2M, BST2, OAS1, and PKR to function against virus infection." (PMID 35910807, 2022). "In the present study, the transcription levels of IFN-β, OAS1, Mx1, and ISG15 in the lungs and intestines of mice pretreated with L. plantarum 0111 were correspondingly increased, and the lung viral load was significantly reduced after viral infection." (PMID 35847111, 2022). "In a previous EPF genome-wide expression study (GWES), several genes involved in the early stages of viral infection were overexpressed in patients with the generalized form of EPF compared to healthy individuals, including IFITM3, APOBEC3A, APOBEC3G, OAS1, OASL, SERINC3, and RPLP2." (PMID 35632621, 2022). "On the contrary, the treatment of α-IFNAR1 mAb did not affect the expression of OAS1, as the virus infection did not activate the expression of IFN-α." (PMID 35062253, 2021).
viral infection (continued). "It was found that OAS1 and OAS3 participated in the activation of RNase L during viral infection." (PMID 32276512, 2020). "Induction of OAS proteins by IFN and viral replication leads to synthesis of 2’5’ oligoadenylates which activate RNase L. OASs (OAS1, OAS2, OAS3) synthesize 2’-5’ oligoadenylates and activate RNase L leading to degradation of viral and cellular RNAs, thereby restricting viral infections." (PMID 30779786, 2019). "A subset of genes including OAS1, OAS2, EFNB2, and CKS1B involved in the immune response to viral infection showed a higher expression level and H3K4me3 enrichment in PEDV-infected samples, suggesting the role of H3K4me3 deposition in promoting their expression." (PMID 31382472, 2019). "In particular, they upregulated transcription of the genes involved in cellular response to viral infection and foreign genetic material, such as RIG-I (DDX58), OAS1, MYD88, RNASEL, PKR (EIF2AK2), as well as interferon-dependent transcription factor STAT and IRF families." (PMID 29986702, 2018). "Human OAS1 and OAS2 have proved to be ineffective for activation of RNaseL upon virus infection." (PMID 30587119, 2018). "These IFNs are essential in the early control of virus infection as they facilitate the induction of over 300 IFN-stimulated genes including MX1, OAS1, and PKR that degrade viral RNAs and induce apoptosis, resulting in an antiviral state in the microenvironment." (PMID 26694447, 2015). "MX1, MX2, and OAS family members OAS1, OAS2, OAS3 mediate resistance to virus infection." (PMID 18648529, 2008). "Finally, the overexpression of MX1, a well-characterized biomarker of viral infection; IFIT1, one of the top upregulated genes; and OAS1, OAS2 and OAS3, genes with a molecular function, 2-5-oligoadenylate synthase activity, identified as enriched in the DGE analyses, was confirmed by RT-qPCR." (PMID 42194954, 2026). "According to related studies, the expression level of OAS1 in anti-viral infection is higher than that of OAS2 and OAS3, and there is a high correlation between the expression of OAS1 and the other three OAS genes, which may indicate the important role of OAS1." (PMID 36162993, 2022). "Furthermore, expression of interferon-stimulated genes such as MX1 and OAS1 was blocked downstream of poly(I:C) transfection by JAK inhibition but not induced by viral infection or METTL3 knockdown." (PMID 33243990, 2020). "The role of OAS1 and the other interferon-related genes in ageing animals and Alzheimer’s disease is not clear, they may be involved in limiting viral infections, recruiting immune cells to sites of damage and/or regulating cytokine production." (PMID 32274467, 2019). "However, the roles of OAS1–3 in individual viral infections have not been fully investigated." (PMID 25550087, 2015). "To investigate whether the antiviral effect of C11orf83 is through OASs-RNase L system, we examined the expression of OAS family four members (OAS1, OAS2, OAS3, and OASL) at the mRNA level in HEK293 cells that only overexpressed C11orf83 but no viral infection." (PMID 28418037, 2017).
breast carcinoma (22 papers, 2010 to 2025). "High expression of OAS1 is correlated with worse prognosis for individuals with breast cancer and a SNP within OAS1 is associated with prostate cancer." (PMID 36503519, 2022). "In breast cancer, elevated OAS1 is associated with poor prognosis." (PMID 35898870, 2022). "Interestingly, OAS1 also is postulated to be associated with radiation resistance in human breast cancer and CaP cell lines and with the regulation of cell growth in mammary and prostate glands." (PMID 21253471, 2010). "Although OAS1 is associated with poor prognosis in certain cancers (such as breast cancer), our data in bladder cancer indicate that high expression of OAS1 correlates with a better prognosis, suggesting that its role may be cancer type-specific and warrants further investigation." (PMID 41584451, 2025). "To further investigate the functional roles of the OAS family genes in breast cancer, we designed four siRNAs targeting OAS1, OAS2, OAS3, and OASL and transfected them into HOC1 cells." (PMID 39633486, 2024). "The results revealed that breast cancer patients exhibiting increased expression of OAS1, OAS2, OAS3, and OASL genes had poor overall survival." (PMID 39633486, 2024). "The mutational spectrum of OAS1, OAS2, OAS3, and OASL genes in breast cancer patients from the TCGA dataset was investigated using the cBioportal database." (PMID 39633486, 2024). "OAS1 protein levels were up-regulated in breast cancer, COAD, ovarian cancer, renal clear cell carcinoma, endometrial cancer, lung cancer, pancreatic cancer, HNSC and glioblastoma, but down-regulated in liver cancer." (PMID 37746262, 2023). "It has been shown that OAS1, as a key regulated gene in breast cancer, and upregulated in breast cancer patients." (PMID 37746262, 2023). "Downregulation of OAS1 in human breast cancer cell line MDA-MB-231T resulted in decreased in vitro motility." (PMID 37686559, 2023). "2’,5’-oligoadenylate synthetase 1 (OAS1), has been reported as a tumor driver gene in breast carcinoma and pancreatic carcinoma." (PMID 37746262, 2023). "It reported that high mRNA expression of OAS1 was tightly related to worse overall survival (OS) in grade 1 breast cancer." (PMID 35254502, 2022). "In breast cancer, prostate and cervix carcinoma cells, elevated levels of OAS1 were reported to decrease cell growth." (PMID 36077645, 2022). "We also find out that OAS1 is a tumor suppressor gene in breast cancer by inhibiting cell proliferation and metastasis, which can be reversed by TINCR to a certain extent." (PMID 33649294, 2021). "Further experiments showed that TINCR promoted the proliferation and metastasis of breast cancer cells by regulating its target gene OAS1." (PMID 33649294, 2021). "Further analysis revealed that TINCR expression was inversely correlated with OAS1 level in breast cancer (Pearson correlation coefficient r = −0.697, r2 = 0.485, P < 0.001)." (PMID 33649294, 2021). "To further explore the role of OAS1 in breast cancer, we first detected the level of OAS1 in 51 pairs of breast cancer tissues and five breast cancer cell lines." (PMID 33649294, 2021). "They determined that the immunoreactivity of OAS1 was inversely correlated with the histological grade of breast cancer, suggesting that OAS1 was related to the invasion of breast cancer." (PMID 33649294, 2021). "The results showed that compared with the adjacent noncancerous tissues and normal breast epithelial cells, the level of OAS1 in breast cancer tissues and cell lines decreased significantly." (PMID 33649294, 2021). "In our study, we find out that TINCR expression was inversely correlated with OAS1 level in breast cancer tissues." (PMID 33649294, 2021). "High mRNA expression of OAS1 and OAS3 was correlated with worse prognosis, while high mRNA expression of OAS2 was associated with better outcomes in all breast cancer patients." (PMID 32560641, 2020).